CAT (catalase)
Diseases named in the same sentence as CAT in open-access papers (continued):
Sharing a sentence is not in itself a finding about the gene and the disease.
sarcopenia (16 papers, 2013 to 2025). Progressive decline in muscle mass due to aging which results in decreased functional capacity of muscles. "In contrast, catalase is inactivated by hydrogen peroxide, and in an animal model of sarcopenia, increased superoxide anion is associated with increased SOD, increased hydrogen peroxide and decreased catalase." (PMID 35874835, 2022). "This hypothesis is sustained by previous observations on pre-clinical models, in which SOD1 depletion causes early sarcopenia, or CAT overexpression reduces the age-dependent loss of muscle quantity and performance." (PMID 38001845, 2023). "The decrease in CAT mRNA in the diaphragm suggests impaired antioxidant defense, which can lead to increased oxidative damage characteristic of sarcopenia." (PMID 39201422, 2024). "Our group also investigated the role of mitochondria‐targeted catalase in skeletal muscle (mMCAT) in redox‐dependent sarcopenia." (PMID 35199907, 2022). "There is evidence that lower levels of CAT characterize the primary inflammatory response during sarcopenia." (PMID 36561214, 2022). "Increased expression of mitochondrial CAT in muscle prevents muscle atrophy in a mouse model of sarcopenia." (PMID 36561214, 2022). "Probably, TNF‐α and catalase are markers of an early inflammatory reaction that is impaired in subjects with sarcopenia." (PMID 33566325, 2021). "The impaired CAT and GPX function was also evident in aging sarcopenia where there is a loss of endogenous enzymatic antioxidant protection against elevated levels of H2O2 in skeletal muscle of aged mice." (PMID 31320913, 2019). "The mitochondrial impairment leads to a redox unbalance, another important issue of sarcopenia; in our experimental condition, DEX caused an increase in both catalase activity and O2− levels that resulted in reduced by glucoraphanin, 3-mercaptopyruvate, and L-cysteine." (PMID 35682634, 2022). "Increased CAT expression inhibits mitochondrial dysfunction, maintains muscle mass and energy production, improves exercise capacity, and prevents reductions in muscle fiber diameter, suggesting that expression of muscular mitochondrial CAT can prevent sarcopenia-related phenotypes." (PMID 36561214, 2022). "A cross-sectional study exploring neuromuscular, peripheral pro‐inflammatory, and oxidative stress molecules as potential biomarkers associated with sarcopenia in old-aged people with hip fracture only found differences in peripheral TNF‐α levels and catalase activity." (PMID 33566325, 2021). "From the results obtained using an experimental model, Sullivan-Gunn and Lewandowski suggested that the decline in antioxidant protection by catalase and GPx is indicative of antioxidant dysfunction and might therefore act as a major contributing factor in the development or onset of sarcopenia." (PMID 29344422, 2017). "This study also suggests that H2O2 is the key ROS in the onset of sarcopenia and that the decline in antioxidant protection by catalase and GPx is indicative of antioxidant dysfunction and may therefore be a major contributing factor in the development or onset of sarcopenia." (PMID 24093947, 2013). "Catalase mRNA was significantly downregulated, suggesting an impaired capacity to detoxify hydrogen peroxide (H2O2) and leaving muscle fibers vulnerable to ROS-mediated damage, typical of sarcopenia." (PMID 40869011, 2025). "The expression of SOD1, CAT, GR, and GS was significantly reduced in patients with sarcopenia compared to non-sarcopenic individuals." (PMID 38001845, 2023). "Furthermore, while this study suggests that H2O2 is the key oxidant in the onset of sarcopenia, the lack of antioxidant protection from catalase and GPx is equally as important, whereas the lack of SOD1 antioxidant protection at 24 months does not appear to contribute to sarcopenia." (PMID 24093947, 2013).
ulcerative colitis (16 papers, 2017 to 2025). An inflammatory bowel disease involving the mucosal surface of the large intestine and rectum. "Kuijieyuan Decoction alleviates the decrease in the relative abundance of Alloprevotella and Prevotella and the decrease in CAT activity in ulcerative colitis rats." (PMID 38671889, 2024). "An experimental model of ulcerative colitis showed antioxidant and anti-inflammatory effects of CoQ10 at a dose of 30 mg/kg by increasing the content of glutathione, catalase activity, reduced malonic dialdehyde level in the colon tissues." (PMID 37242469, 2023). "Many studies have revealed that SOD, GSH, and catalase levels were reduced in colon during experimental ulcerative colitis." (PMID 33995942, 2021). "The aim of the present study was to analysis the relationship between the genetic polymorphisms of SOD1, CAT and GSHPX1 and the prevalence of IBD, including Crohn’s disease and ulcerative colitis among the Polish population." (PMID 29312611, 2017). "In ulcerative colitis, the expressions of CAT and GPx are significantly upregulated." (PMID 40646747, 2025). "The main aim of this study was investigate the association between the genetic polymorphism of antioxidant enzyme genes: SOD1, CAT and GSHPX1 and the risk of inflammatory bowel disease (IBD), including Crohn’s disease and ulcerative colitis in the Polish population." (PMID 29312611, 2017). "The research findings indicate that cinnamic acid has the potential to reduce ulcerative colitis (UC) induced by dextran sodium sulfate (DSS) by reducing MDA levels and increasing total SOD and CAT levels." (PMID 40872532, 2025). "In comparison to the control group, levels of MDA showed a significant increase, whereas total levels of superoxide dismutase (SOD) and catalase (CAT) exhibited a notable decrease, resulting in the development of ulcerative colitis." (PMID 40872532, 2025). "Particularly at the intestinal level, acrylamide was shown to accelerate the development of ulcerative colitis in mice, presenting reduced levels of glutathione (GSH), catalase (CAT), superoxide dismutase (SOD), and IL (interleukin)-10." (PMID 38247489, 2024). "To further verify the effect of the free polyphenol extract of cherry on ulcerative colitis in mice, we measured the activity of enzymes (ALT, CAT, GSH-Px, SOD), and the levels of inflammatory cytokines (MDA, MPO, NO)." (PMID 35010176, 2021).
cardiomyopathy (15 papers, 2010 to 2025). A disease of the heart muscle or myocardium proper. "As oxidative stress is regarded as the primary cause of DOX-induced cardiomyopathy, we detected the levels of oxidative stress markers (CAT, SOD, MDA, GSH, GSH-Px) in rat heart tissues." (PMID 34565300, 2021). "In contrast, overexpression of both SOD2 and catalase protects the cell from antiretroviral-induced oxidative stress and cardiomyopathy." (PMID 33504070, 2021). "Of interest, cardiomyopathy triggered by the ablation of desmin, a major muscle-specific intermediate filament protein, is ameliorated by catalase overexpression but deteriorated by SOD2 overexpression." (PMID 33504070, 2021). "Together, our results provide a new insight in treating DMD cardiomyopathy via targeting of CAT and VCAM1, and serves as an example of translating Bed to Bench back to Bed using a muti-omics approach." (PMID 33869226, 2021). "Mechanistically, we found that the cardiac protection by Zn and BSE from IH-induced cardiomyopathy is associated with significant increases in MT- and Nrf2-mediated antioxidants, including NQO-1, SOD-2, and CAT." (PMID 31934264, 2019). "In order to more decisively determine if elevated ROS contributed to mtCaMKII cardiomyopathy, we took an orthogonal approach, and interbred mtCaMKII mice with mice transgenically overexpressing a mitochondrial-targeted form of catalase (mCat), an enzyme that decomposes H2O2 into H2O and O2." (PMID 32887881, 2020). "Based on our multi-omics analysis, we identified and validated CAT and VCAM1 as novel targets for treating DMD cardiomyopathy." (PMID 33869226, 2021). "Similarly, our findings indicate that the anti-oxidant effects of both LGG and LGGs against IH-induced cardiomyopathy were mediated via activation of Nrf2 and its target genes (such as HO-1, NQO1, and CAT)." (PMID 31595164, 2019). "This study has shown that DOX produced significant cardiomyopathy, as evidenced by increased levels of serum marker enzyme (LDH) and tissue TBARS; decreased levels of myocardial endogenous antioxidants (glutathione, superoxide dismutase, and catalase)." (PMID 20606837, 2010). "Artificial intelligence tools and integrative data analysis revealed superoxide dismutase, catalase, glutathione peroxidase, gap junction protein α, myosin heavy chains, and zinc finger transcription factor GATA4 are engaged in oxidative stress and in cardiomyopathy." (PMID 35311161, 2022). "The activity of CAT in the control and ISO groups did not significantly differ; however, aqTAX treatment enhanced the activity of this enzyme in animals with ISO-induced cardiomyopathy." (PMID 39519147, 2024).
cataract (15 papers, 2011 to 2025). Partial or complete opacity of the crystalline lens of one or both eyes that decreases visual acuity and eventually results in blindness. "The aim of the present study was to investigate the association between NQO1 C609T (Pro189Ser, rs1800566) and CAT promoter C-262T (rs1001179) genetic polymorphisms and the susceptibility to cataracts." (PMID 27844006, 2015). "Studies indicate that patients with cataracts have lower serum CAT and SOD levels than healthy controls." (PMID 37238957, 2023). "In turn, other studies demonstrate lower plasma antioxidant capacity, but higher SOD and CAT activity in erythrocytes of presenile and senile cataract patients in comparison with healthy persons." (PMID 37238957, 2023). "H2O2-induced cataracts were linked to reduced SOD2 and CAT activities and reinforced NQO-1 activity of the lens." (PMID 35222803, 2022). "Compared with the control group, the activities of SOD, GSH-Px, and CAT in cataract group were lower than those in the control group (P < 0.05, P < 0.01)." (PMID 23781296, 2013). "In the present study, we found that there was a significant decrease in the activity of SOD, GSH-Px, and CAT in serum of cataract patients, compared with normal control." (PMID 23781296, 2013). "Additionally, lutein and water chestnut extract reduced the lens opacity in rats with cataracts and increased peroxiredoxin 6 and catalase expression both in rats with cataracts and human lens epithelial cells." (PMID 39334773, 2024). "This includes glutathione peroxidase, for which knock-out mice develop age-related cataracts and catalase, which contributes to degradation of hydrogen peroxide in the lens, even though knocking it out in a mouse model does not cause cataracts." (PMID 39594457, 2024). "Simultaneous involvement of both enzymes in the disposal of hydrogen peroxide produced in excess has been revealed in our cataract patients with indicated positive and statistically significant correlation between the activity of GPx and CAT in erythrocytes (r = 0.530, p = 0.008)." (PMID 37238957, 2023). "Genotype distributions of NQO1 and CAT polymorphisms were examined using polymerase chain reactions and a restriction fragment length polymorphism (PCR-RFLP) approach to investigate the possible role of these polymorphisms as risk factors in the development of cataracts." (PMID 27844006, 2015). "It is particularly beneficial for various ocular conditions, such as dry eye, keratitis, cataracts, diabetic retinopathy, macular degeneration, high IOP, and optic nerve-related diseases, by increasing catalase, SOD, and GSH peroxidase activity." (PMID 39859017, 2024). "Compared with the control group, the activities of SOD, GSH-Px, and CAT in cataract group were lower than those in the control group and the oxidative stress products MDA, 4-HNE, CD, AOPP, PC, and 8-OHdG were significantly increased in serum in cataract patients." (PMID 23781296, 2013). "Moreover, we found compensatory overexpression of antioxidant enzymes (SOD1, GPx‐1, and catalase) in aged lenses with cataracts in VEGF‐Ahyper mice, but not in young lenses without cataracts." (PMID 26912740, 2016).
cervical cancer (15 papers, 2009 to 2025). A primary or metastatic malignant neoplasm involving the cervix. "Cervical cancer patients had lower levels of antioxidant indicators such as erythrocyte superoxide dismutase, catalase, glutathione peroxidase, and glutathione transferase." (PMID 38374844, 2024). "For instance, PG upregulates the activity of superoxide dismutase (SOD) and catalase (CAT) in HeLa cervical cancer cells." (PMID 38438412, 2024). "Morinda citrifolia (Noni) alters oxidative stress marker, MDA content and antioxidant activity (SOD and CAT) in the cervical cancer cell lines." (PMID 31013662, 2019). "It has been reported that CAT is also decreased in HCC but increased in cervical cancer." (PMID 36035213, 2022). "PGRN enhances the ROS scavenger system, as evidenced by increased superoxide dismutase (SOD), catalase protein expression and activity, elevated GSH and NADPH levels and increased phase II detoxification enzyme expression in cervical cancer cells after serum withdrawal." (PMID 39695087, 2024). "Similarly, human cervical cancer cells treated with GO silver nanocomposite exhibited decreased levels of SOD and CAT in human cervical cancer cells." (PMID 30634552, 2019). "We investigated whether apigenin exposure induces oxidative stress in cervical cancer cells using assays to detect total ROS and H2O2 production, changes in mitochondrial membrane potential (ΔΨm), lipid peroxidation (LPO) levels, and catalase activity." (PMID 28191273, 2017). "This lack of effect may result from cervical cancer cells’ enhanced tolerance to oxidative stress, supported by high endogenous antioxidant enzyme levels, such as superoxide dismutase and catalase." (PMID 40361715, 2025).
chronic kidney disease (15 papers, 2012 to 2025). Impairment of the renal function secondary to chronic kidney damage persisting for three or more months. "In this study, we sought to test if expression of a mitochondrial targeted catalase (mCAT) in skeletal muscle could reduce AVF-related limb dysfunction in mice with chronic kidney disease (CKD)." (PMID 38594299, 2024). "Effects of Shenkang injection (SKI) on the levels of CAT, SOD, GSH-PX, and MDAin the serum of chronic renal failure rats*." (PMID 35674582, 2022). "In this study, we examined the levels of nitric oxide (NO), malondialdehyde (MDA), catalase (CAT), and superoxide dismutase (SOD) in serum and renal tissues of rats with adenine-induced chronic renal failure." (PMID 31915448, 2019). "In addition, treatment with melanin prevented adenine-induced chronic renal failure in mice and cisplatin-mediated nephrotoxicity by suppressing MAD, upregulating GSH, SO, GPx, and CAT, and inhibiting the production of TNF-α and IL-6." (PMID 36838869, 2023). "Marked decreases in activities of superoxide dismutase, catalase, and glutathione peroxidase, as well as reduced glutathione (GSH) levels, were also observed in blood samples from patients with chronic renal failure, possibly as a result of defective mitochondrial antioxidant capacity." (PMID 34248614, 2021).
inflammatory bowel disease (15 papers, 2015 to 2025). A spectrum of small and large bowel inflammatory diseases of unknown etiology. "The artificial enzyme FeSA, mimicking the functions of SOD and CAT, has been incorporated into Bifidobacterium longum (BL) probiotics for the treatment of inflammatory bowel disease (IBD)." (PMID 39766345, 2024). "Some studies suggest that catalase and glutathione peroxidase concentrations correlate significantly with fecal calprotectin levels in patients with inflammatory bowel disease." (PMID 37298198, 2023). "It is noteworthy that CAT is involved in apoptosis and its administration has been used to prevent or decrease the severity of certain intestinal pathologies and inflammatory bowel diseases." (PMID 36555526, 2022). "Oxidative stress significantly contributes to the initiation and progression of inflammatory bowel disease (IBD), and the induction of CAT and superoxide dismutase (SOD) as free radical scavengers can mitigate the expression of pro-inflammatory mediators." (PMID 40430897, 2025). "Therefore, eliminating ROS in the inflammatory site by antioxidant enzymes such as catalase and superoxide dismutase may effectively curb inflammatory bowel disease (IBD)." (PMID 35701435, 2022). "In inflammatory bowel disease model, Lactobacilli with SOD or CAT activity alleviated the inflammation." (PMID 39766345, 2024).